GDF15 (growth differentiation factor 15)
Diseases named in the same sentence as GDF15 in open-access papers (continued):
Sharing a sentence is not in itself a finding about the gene and the disease.
Cachexia (142 papers, 2012 to 2026). Severe weight loss, wasting of muscle, loss of appetite, and general debility related to a chronic disease. "At T1, cachexia was strongly associated with elevated GDF15 (OR 4.29; 95% CI 1.04-29.74; p = 0.044) and IL-15 (OR 43.83; 95% CI 2.39->999; p = 0.007), whereas IL-4 had a protective association (OR 0.09; 95% CI 0.00-0.66; p = 0.013)." (PMID 41749907, 2026). "Among these were PTHrP, GDF15 and interleukin-6, all of which have been linked to cachexia in various settings." (PMID 41315757, 2026). "Growth Differentiation Factor 15 (GDF15) is a key mediator of cachexia-associated anorexia and tissue wasting; however, the upstream mechanisms regulating its expression in gastric cancer remain poorly defined." (PMID 41744798, 2026). "Levels of GDF15 are increased in patients with cardiac cachexia and are closely associated with myocardial fibrosis, impaired cardiac function, and the severity of cachexia." (PMID 40837873, 2025). "Animal studies have shown that monoclonal antibodies targeting GDF15 can prevent weight loss and the onset of cachexia while also slowing the deterioration of cardiac function." (PMID 40837873, 2025). "Elevated levels of circulating GDF15 are consistently found in patients with cancer cachexia and are correlated with anorexia, weight loss, and decreased survival." (PMID 40869331, 2025). "Supporting the role of the GDF‐15‐GFRAL axis in cachexia, cisplatin‐induced anorexia and muscle loss were attenuated in GFRAL knockout mice." (PMID 40343378, 2025). "For example, GDF-15 has been linked to appetite suppression and muscle wasting in specific cachexia subtypes and is currently under investigation as a clinical biomarker." (PMID 40759570, 2025). "Among these were PTHrP, GDF15, and IL-6, all of which have been linked to cachexia in various settings 18,19,30,31." (PMID 40964365, 2025). "Further research must be done in this area, specifically in paediatric cancers with the highest risk of cachexia, to further elicit the effect of tumour type and treatment on GDF15 and subsequent development of cachexia." (PMID 40019842, 2025). "In an open-label phase 1b study involving cancer cachexia patients with elevated GDF15 levels, ponsegromab was associated with improved weight, appetite, and physical activity." (PMID 40837873, 2025). "GDF15 inhibition is associated with weight gain, and GDF15 overexpression is believed to mediate cancer-associated anorexia/cachexia by activating GFRAL." (PMID 40354065, 2025). "Overall, these data show that tumor growth led to a significant increase in circulating levels of IL-6 and GDF15 before the onset of anorexia-cachexia, the latter being associated with plasma concentrations of these two cytokines above threshold values." (PMID 40124481, 2025). "The independent, causal effects of GDF15 on cachexia, inflammation and other diseases remains debated." (PMID 40019842, 2025). "For example, cisplatin, while effective in tumor suppression, induces a progressive increase in GDF-15 and a decline in ghrelin levels over time, leading to appetite loss, reduced physical activity, and worsening cachexia symptoms." (PMID 40759570, 2025). "In a mouse model of cancer‐induced cachexia characterized by high circulating GDF15 levels and pathological weight loss, administration of a GDF15‐neutralizing antibody induced pronounced weight regain in female mice; male mice were not assessed." (PMID 40787810, 2025). "On the other hand, pancreas carcinoma and pancreatitis are strongly associated with nausea, reduced food intake and anorexia/cachexia, and are obviously mediated by the GDF15/GFRAL brainstem pathway." (PMID 38474863, 2024). "Elevated levels of GDF15 have been associated with cachexia and reduced survival rates in cancer patients." (PMID 39172988, 2024).
Cachexia (continued). "Recently, animal studies have associated GDF-15 with the induction of appetite and weight loss, cachexia, increased oxidative metabolism, and upregulation of crucial thermogenetic and lipolytic genes." (PMID 38890300, 2024). "Our findings reveal that elevated serum GDF-15 levels are significantly associated with shorter mPFS and mOS, as well as an increased risk of developing cancer-associated cachexia." (PMID 39766045, 2024). "The expression level of GDF15 is closely associated with the occurrence and development of cachexia." (PMID 39172988, 2024). "In depth investigations should be undertaken to identify how to best balance the benefits of GDF15 supplementation against its risks, including anorexia/cachexia and weight loss." (PMID 39737171, 2024). "Despite the development of GDF-15 mimicking compounds for weight loss and the ongoing development of GDF-15 inhibitors against cachexia and conditions of metabolic stress." (PMID 38890300, 2024). "This suggests a statistically significant association between elevated GDF-15 levels and the development of cancer-related cachexia." (PMID 39766045, 2024). "Through the activation of the GFRAL (GDNF-family receptor α-like)-RET (Rearranged during Transfection) signaling pathway, GDF15 can induce weight loss, making it a potential target for treating cachexia." (PMID 39172988, 2024). "Growth differentiation factor-15 (GDF-15), previously associated with anorexia, nausea, weight loss, and cachexia in cancer patients, is also elevated in patients with HF and has been associated with a lower exercise capacity, lower BMI, and higher mortality." (PMID 37176761, 2023). "The GDF-15 has been shown to signal through the glial cell-derived neurotrophic factor (GDNF) family receptor α-like (GFRAL), which is solely expressed in the human brain stem and is associated with GDF-15-mediated anorexia and cachexia." (PMID 37905271, 2023). "Our findings provide insights that the risk for GDF15 overexpression and concomitant cachexia can be reduced by a personalized selection of anticancer drugs and patients for precision medicine." (PMID 37495707, 2023). "Further, antibody mediated antagonization of GFRAL mitigated weight loss and preserved muscle mass in cancer cachexia mouse models with high‐circulating GDF‐15." (PMID 36642986, 2023). "Animal models investigating the association of GDF-15 and cancer-induced cachexia further underscore its significance." (PMID 37755304, 2023). "In a preclinical mouse model of cancer-induced cachexia, GDF15 neutralization alleviated weight loss and restored muscle mass and function." (PMID 37813923, 2023). "We used an orthogonal GDF15-specific serological assay, demonstrating that circulating GDF15 levels correlated significantly with loss of SAT, VAT, SKM and body weight, suggesting a cachexia-mediating role for GDF15 in patients with NSCLC." (PMID 37045997, 2023). "The positive association of circulating GDF15 with weight loss in rats prompted us to examine if elevated GDF15 by MCT is causal to cachexia in vivo." (PMID 35406637, 2022). "For instance, FGF21 can affect food intake, appetite, or food preference, and GDF15 which can also be released from autophagy-deficient tumors can induce cachexia associated with cancer." (PMID 35321438, 2022). "Previous studies have verified that GDF-15 can cause cachexia and targeting GDF-15 in animal models rescued weight loss." (PMID 35379793, 2022). "The stress factor GDF15 is frequently upregulated in cachexia, in both patients and preclinical models, and is implicated in anorexia, adipose and muscle wasting, making it a promising therapeutic target for cachexia syndrome." (PMID 36158184, 2022). "GDF15 has been reported to play a causal role in cancer cachexia, and GDF15 neutralization appears to be efficacious in mitigating tumor-induced cachexia preclinically." (PMID 35406637, 2022).
Cachexia (continued). "High levels of GDF15 were reported in cancer patients with cachexia, manifesting great loss of adipose tissue and skeletal muscle." (PMID 35202387, 2022). "GDF15 has a strong effect on anorexia and can affect metabolism, potentially causing skeletal muscle wasting and lipolysis in cancer cachexia." (PMID 36105371, 2022). "GDF15 is also implicated in energy homeostasis, body weight regulation, and plays a distinct role in cachexia." (PMID 33442410, 2021). "High circulating levels of GDF-15 in cancer patients have been associated with chemoresistance, anorexia, emesis and weight loss, all of which are symptoms of cachexia." (PMID 34638326, 2021). "Another study revealed that the inhibition of GDF15 restored muscle and appetite to reverse cancer-associated cachexia in animal models." (PMID 35083256, 2021). "As such, it is thought that an elevated GDF-15 level results in loss of appetite, anorexia, and cachexia, and directly affects muscle wasting and consequent weight loss." (PMID 34247467, 2021). "It has been previously reported that GDF15 causes anorexia/cachexia via its impact on energy metabolism and, accordingly, it is found inversely associated with muscle mass." (PMID 32477368, 2020). "In humans with chronic diseases and malignancies, GDF15 can suppress appetite and induce weight loss even in cachexia." (PMID 33178828, 2020). "Using genetically engineered xenograft mouse models, the activation of mitogen-activated protein kinase kinase kinase 11 (MAP3K11) by GDF-15 was identified as the key trigger for weight loss in animal models of cancer-related cachexia." (PMID 32508832, 2020). "The most obvious route to clinical utility is in the use of GDF15 antagonists in chemotherapy-induced nausea and vomiting and in various forms of cachexia associated with high circulating GDF15." (PMID 32310257, 2020). "Since it was previously reported that supraphysiologic overexpression of GDF11 in the liver of young mice induced weight loss and cachexia through activation of GDF15 and anorexia, we sought to examine this in our paradigm of systemic rGDF11 administration." (PMID 31637864, 2020). "Higher circulating GDF15 levels in fact were found to be associated with the development of cachexia in both animal models and human patients." (PMID 32757036, 2020). "Raised serum C-reactive protein (CRP), a biomarker for systemic inflammation, interleukin 6 (IL6), and growth differentiation factor-15 (GDF-15) are thought to be associated with cachexia." (PMID 31323984, 2019). "Animal studies also showed that GDF15 causes anorexia/cachexia, and then weight loss through a direct effect on the hypothalamus." (PMID 31581569, 2019). "In cancer, it is reported that elevated serum levels of GDF15 cause cancer-induced anorexia and cachexia directly through circulating GDF15 on feeding centers in the brain." (PMID 28206960, 2017). "Intriguingly, both myostatin and GDF15 have been associated with cachexia, a common and often fatal condition which occurs most commonly in advanced cancer." (PMID 27916875, 2016). "This is consistent with an accumulating number of studies showing associations between higher GDF‐15 activity (expression, circulating levels) and physical and mental capacities, functional ability, sarcopenia and cachexia at older age, surrogates of the endpoint here investigated." (PMID 41560403, 2026). "Conversely, GDF15 inhibitors could mitigate its potential detrimental effects, such as β-cell apoptosis or cancer-associated cachexia, in specific pathological contexts." (PMID 40837873, 2025). "By analyzing 85 patients with advanced cancers such as lung, kidney, and melanoma, we discovered that high levels of GDF-15 were associated with worse survival outcomes and a higher likelihood of cancer-related cachexia, a condition causing severe weight and muscle loss." (PMID 39766045, 2024). "Research has found that GDF15 is a major causative factor of chemotherapy-induced cachexia." (PMID 39172988, 2024).
Cachexia (continued). "Elevated circulating levels of GDF-15 may lead to anorexia, weight loss and decreased in survival in patients with cancer cachexia." (PMID 39394174, 2024). "Typically, GDF15 levels are significantly elevated in cachectic patients, and its upregulation is thought to be closely related to the physiological and pathological processes associated with cachexia, including muscle degradation and abnormal fat metabolism." (PMID 39172988, 2024). "GDF15 is an inflammatory biomarker released by various tissues, and elevated circulating levels of GDF15 are associated with anorexia, malaise, and cachexia in a variety of diseases and physiological states." (PMID 37474864, 2023). "Elevated circulating GDF15 is associated with cachexia and poor survival in cancer patients." (PMID 35406637, 2022). "Animal experiments showed that mice injected with recombinant GDF15 or transplanted with GDF15 overexpression tumor showed decreased food intake and weight loss, whereas mice with cachexia treated with an anti‐GDF15 antibody show weight gain and muscle and adipose tissue recovery." (PMID 36105371, 2022). "GDF15 persuades weight loss via the suppression of appetite, thus neutralizing antibodies against the GDF15 may reduce cancer-mediated cachexia." (PMID 36140453, 2022). "On the other hand, patients with elevated GDF-15 levels (group F), who might be at risk of anorexia-cachexia, had more than 4-fold elevation of risk for cancer and CV death compared with those with non-elevated GDF-15 (Group C)." (PMID 34150865, 2021). "In addition, elevated circulating levels of GDF15 were correlated with the onset and progression of cachexia in mice and in patients with cancer, which causes symptoms similar to HG, such as nausea, weight loss, and muscle wasting." (PMID 35083256, 2021). "One possible explanation for a worse survival of GDF15+GFRAL+RET-coexpressing GC patients could be cancer-associated cachexia." (PMID 34149933, 2021). "The secretion of GDF15 from various malignant tumors and its mediation of tumor-associated cachexia and weight loss was established in 2007 and even earlier (in 2000) it was shown that the placental trophoblast is a major source of GDF15 in maternal plasma and amniotic fluid." (PMID 34831213, 2021). "The serum GDF-15 levels in patients with low BMI might be a useful marker to identify the potential for anorexia-cachexia associated with CVD and cancer." (PMID 34150865, 2021). "Because elevated GDF-15 levels could cause body weight loss through effects on the appestat, serum GDF-15 levels might be a useful marker to identify the potential anorexia-cachexia in patients with low BMI." (PMID 34150865, 2021). "However, the finding that loss of muscle mass depends on GDF-11, whereas GDF-15 is mainly responsible for anorexia, would seem to indicate that such drugs would be of limited usefulness in cancer patients with wasting syndrome." (PMID 32508832, 2020). "First, an increase of GDF-15 may cause appetite loss, anorexia, and cachexia as shown in patients with cancer." (PMID 31581569, 2019). "In contrast, the long-term consumption of a high-fat diet, commonly associated with a KD, may promote cachexia due to the increase in GDF-15." (PMID 31323984, 2019). "GDF15 is produced in large amounts by cancer cells and may act on feeding centres in the hypothalamus and brainstem to cause anorexia and eventually cachexia leading to loss of lean and fat mass." (PMID 27916875, 2016). "Since our current data have shown that circulating GDF15 is a risk factor for infectious complications in patients with EC, GDF15 may be useful for predicting blood biomarkers of cachexia which can lead to infectious complications in patients with EC who have undergone curative esophagectomy." (PMID 41016991, 2026).
Cachexia (continued). "Therefore, in this study, we evaluated the correlation between clinical data suggesting cachexia in patients with Esophageal Cancer (EC) and plasma GDF15 to assess the usefulness of GDF15 as a potential biomarker for cachexia and risk factors for postoperative complications." (PMID 41016991, 2026). "Thus, GDF-15 may be a potential biomarker for pre-cachexia (prior to weight loss) in the White and the Hispanic population, but not Black individuals." (PMID 39989973, 2025). "Additionally, high GDF-15 levels were linked to increased cachexia incidence (p = 0.037)." (PMID 39766045, 2024). "Thus, chemotherapy-induced GDF15 overexpression followed by the concomitant risk for developing cachexia could be reduced." (PMID 37495707, 2023). "We aimed to evaluate whether circulating GDF-15 level could be associated with cachexia symptoms, which include loss of skeletal muscle mass, systemic inflammatory reaction, poor performance status, anorexia, shortened survival time and biological tumor activity in advanced pancreatic cancer (APC)." (PMID 34638326, 2021). "Emerging evidence supports the use of AI-based body composition analysis and novel biomarkers, including GDF-15 levels, to improve the detection and monitoring of cachexia." (PMID 41976282, 2026). "This study evaluated the correlation between clinical data suggestive of cachexia in patients with EC and circulating GDF15 levels." (PMID 41016991, 2026). "Collectively, these findings implicate tumor-derived GDF15 as a key mediator and therapeutic target in STK11/LKB1-mutant NSCLC-associated cachexia." (PMID 41617691, 2026). "Juli E. Jones recently demonstrated that elevated GDF11 induces cachexia in mice, reducing muscle mass, food intake and body weight while upregulating plasma GDF15." (PMID 40969368, 2025). "Novel research in the creation of GFRAL antagonists, thus inhibiting GFRAL dependent GDF15 response, have shown promise in reducing cachexia in in vivo models." (PMID 40019842, 2025). "GDF15 has recently been identified as a potential clinical biomarker to detect the progression and development of cachexia in cancer patients." (PMID 40558549, 2025). "We found elevated circulating levels of IL-6 and GDF15 at established cachexia, in agreement with previous studies using the C26 tumor-bearing mouse model, but also moderately increased levels of these cytokines at the pre-Cx stage." (PMID 40124481, 2025). "Particularly, IL-6 and GDF15 have been functionally involved in animal models of cancer anorexia-cachexia." (PMID 40124481, 2025). "Classified as a myokine, GDF15 shows an inverse relationship between its circulating levels and muscle mass in cancer cachexia." (PMID 40837873, 2025). "In our previous study investigating the effects of GDF15 neutralization in a mouse model of cancer cachexia, we found that the beneficial effects on muscle function and physical performance are primarily attributed to increased caloric intake." (PMID 39976232, 2025). "Growth Differentiation Factor 15 (GDF-15) is involved in anorexia and weight loss common in cancer cachexia." (PMID 40519290, 2025). "Conversely, GDF15 showed positive correlations with the presence of cachexia when defined by IPF Cachexia Syndrome (r = 0.27) and Martin (r = 0.32)." (PMID 40944130, 2025). "In a phase 2 trial involving 187 patients with cancer cachexia and elevated GDF15 levels, ponsegromab enabled patients to regain body weight within 12 weeks, with improvements in appetite, physical activity levels, and skeletal muscle mass." (PMID 40837873, 2025). "Research is also providing insights to improve supportive care, as in a trial which demonstrated improvement of cachexia through inhibition of the growth differentiation factor 15 (GDF-15)." (PMID 40297809, 2025). "The biological activities of GDF15, including anorexia and cachexia, are primarily mediated through the GFRAL receptor, localized in the brainstem and functioning via RET co‐receptor recruitment." (PMID 39907315, 2025).